TNF (tumor necrosis factor)
Diseases named in the same sentence as TNF in open-access papers (continued):
Sharing a sentence is not in itself a finding about the gene and the disease.
psoriasis (continued). "The tumor necrosis factor (TNF)-α and interleukin (IL)-17 remained the most common drug targets (17/60, 28.3% for TNF-α and 18/60, 30.0% for IL-17) in the past 5 years, and all trials on TNF-α and IL-17 were for psoriasis." (PMID 35529441, 2022). "Out of three cytokines with activity leading to psoriasis (IL23 p19, TNFα, and IL17), IL23 p19 may be the most specific, as fewer adverse events occurred in patients treated with guselkumab." (PMID 35563285, 2022). "First, 7 articles were selected to assess the difference in psoriasis development between IBD patients who were treated or not treated with anti-TNF agents." (PMID 35801760, 2022). "We conducted this study to evaluate miR-203 expression level in the plasma of psoriasis patients to investigate its role and target genes SOCS3, SOCS6, P63, TNF-α, IL-8, and IL-24 in the systemic pathogenesis of this disease and correlate these data with the disease course." (PMID 36341243, 2022). "For example, data supports that TNF-activated macrophages are required for the pathogenesis of psoriasis, rather than other immune cell types, even though other cells contribute to the disease." (PMID 35440548, 2022). "All anti-TNF treatments did not increase the risks of psoriasis development relative to treatment without anti-TNF agents." (PMID 35801760, 2022). "In particular, serum levels of IL-17A were strongly correlated with IL-1α, IL-15, IFN-γ, IL-18, TNF-α, IL-12B, IL-17F, and IL-22 in psoriasis but not in healthy controls." (PMID 36118416, 2022). "These preclinical findings suggest that the benefit of R. mucosa in mouse models of psoriasis would most likely operate through either modulating TNF signalling or non-specific pathways that aide in tissue repair." (PMID 36605199, 2022). "Patients with IBD are more likely to develop psoriasis than the non-IBD population regardless of the use of anti-TNF agents." (PMID 35801760, 2022). "Previous studies have reported that IL‐1β, IL‐17A, and TNF‐α may predict the treatment response to TNF inhibitors in inflammatory or rheumatic diseases, such as psoriasis and Crohn disease." (PMID 35694730, 2022). "Since cytokines can have high biological activity even at small concentrations, the levels of TNF-α and IFN-γ, two signature cytokines found in psoriasis, were subsequently measured in the supernatant of HS, PS, PS+T and PS+T+ALA, using independent ELISA assays." (PMID 35563819, 2022). "Anti-TNF agents have shown therapeutic efficacy in both IBD and psoriasis." (PMID 35801760, 2022). "In psoriasis, S. aureus infection can also be mediated by the RIPK1/RIPK3/MLKL-mediated necrotizing apoptosis of keratinocytes, and RIPK1 mediates keratinocyte death via TNF." (PMID 35878202, 2022). "Of considerable interest, the correlation matrix revealed a distinct cytokine panel where cytokines (IFN-γ, IL-18, TNF-α, IL-12B, IL-17A, IL-17F, and IL-22) were positively correlated with each other in psoriasis patients but not in healthy controls." (PMID 36118416, 2022). "Cytokine interactions in psoriasis can rely on the assumption that a linear relationship between inducers (IL-23 or IL-12), the production of IFN-γ and TNF by T cells, and the activation of multiple IFN-responsive genes via signal relay and transcription activator (STAT1) exists." (PMID 35163855, 2022). "In this study, we analyzed CNVs associated with the different phenotypes (plaques vs. pustules) and predominant locations of psoriasis (scalp, non-scalp, and palmoplantar plaques) as well as with anti-TNF-induced PPP." (PMID 36143237, 2022). "For adults with psoriasis who switch between TNF-α antagonists, prior inefficiency of biologics did not appear to affect the treatment outcomes for people switching from etanercept to adalimumab." (PMID 36160145, 2022). "Our study found that the psoriasis development did not increase after anti-TNF therapy in patients with IBD." (PMID 35801760, 2022).
psoriasis (continued). "Likewise, keratinocyte expression of CERS6 was decreased after incubation with TNF and IL-17A, which also mimicked the downregulation of CERS6 in psoriasis lesional skin." (PMID 35900871, 2022). "Regarding psoriasis, a study in which IL-1 inhibition was used in plaque psoriasis showed a decrease in PASI of only 13%, which was lower than that obtained with other biologic agents (anti-TNF, anti-IL-17, and anti-IL-12/-23p40)." (PMID 35743091, 2022). "Such is the case of ixekizumab, an IL-17A inhibitor which, according to data from a recent RCT, improved depressive symptoms in patients with psoriasis, whereas TNF-α inhibitor etanercept did not, suggesting a particular role of IL-17A in the CNS." (PMID 36291336, 2022). "Furthermore, curcumin intervention in T cells obtained from a mouse model of psoriasis showed that 10 μM curcumin concentration significantly blocked the secretion of IL-17, IL-22, IFN-γ, IL-2, IL-8 and TNF-α." (PMID 35979355, 2022). "However, it has been shown that anti‐TNF‐α agents, especially adalimumab and infliximab, may exacerbate established vitiligo and induce new-onset vitiligo during treatment of other autoimmune diseases, including AS, Crohn’s disease, ulcerative colitis, psoriasis, and RA." (PMID 36119071, 2022). "Aberrant PLD/PtdOH signaling activates phosphodiesterase (PDE) 4 family members in a Camp-dependent manner, which further activates cascade of several signaling steps (e.g., PKA/CREB/NFκb), leading to increased proinflammatory cytokines TNF-α, IL-23, IFN-β and γ and promote psoriasis progression." (PMID 36700214, 2022). "Indeed, the efficacy of TNF-α inhibitors and UST is reduced in obese/overweight patients with psoriasis, with consequences for both adherence and persistence." (PMID 35329831, 2022). "These activated dendritic cells release inflammatory cytokines, such as TNF-α, IFN-γ, and interleukin-17 (IL-17), and in return, these cytokines promote keratinocyte proliferation and psoriasis progression with the involvement of the TLR4/NF-κB signaling pathway." (PMID 36233237, 2022). "Anti-TNF antibody therapy was developed to decrease inflammation in a variety of diseases such as inflammatory bowel disease (IBD), psoriasis, psoriatic arthritis, RA, ankylosing spondylitis, and juvenile idiopathic arthritis, emphasizing the role of TNF signaling in several illnesses." (PMID 36428505, 2022). "In the absence of TNF, maturation of pDCs decreases, and their IFNα production is extended, driving a phenomenon called paradoxical psoriasis, which was introduced as a side effect of anti-TNF therapy." (PMID 35207521, 2022). "Cytokines, e.g. TNF, IL1β, IL5, IL6, IL12 and IL23, represent important therapeutic targets in immune-mediated inflammatory diseases (IMIDs), such as inflammatory bowel disease (IBD), psoriasis, asthma, rheumatoid and juvenile arthritis." (PMID 35731827, 2022). "The dysfunction in psoriasis includes systemic inflammation involving cytokines, such as IL-17, TNF-α and IFN-γ, as well as inflammatory transcripts such as CXCL10, IL-1β and VCAM-1.Psoriasis increases vascular stiffness and atherosclerosis tthrough the IL-17 pathway." (PMID 36211578, 2022). "In the presented study, the concentrations of NET protein–PAD-4 and its main stimulus factor, TNFα, were analyzed before and during (week 4 and 12) the application of three types of systemic therapy used in patients with psoriasis: MTX, anti-TNFα and anti-IL 17a." (PMID 35886575, 2022). "Not just limited to the liver, the synergistic effect of TNFα and IL-17 on periostin expression has also been noted in other inflammatory diseases, such as psoriasis, in which it leads to altered keratinocyte differentiation." (PMID 35056404, 2022). "Initially, psoriasis was considered a Th1-mediated inflammatory disease, especially with the involvement of interferon IFN-γ, along with the contribution of tumor necrosis factor TNF-α and interleukin IL-2." (PMID 35888633, 2022).
psoriasis (continued). "Therefore, we established psoriasis-like HPK by treating HPK with the cytokines IL-17A, TNF-α and IL-22." (PMID 33801280, 2021). "Given the importance of TNF-α and the PI3K/AKT pathway in the psoriatic phenotype, we anticipate that oxyresveratrol, which targets the TNF-α-stimulated PI3K/AKT pathway, would represent a promising psoriasis therapy in the near future." (PMID 35056961, 2021). "Insulin sensitivity has been improved by another TNF-α inhibitor adalimumab in psoriasis patients without diabetes." (PMID 34803716, 2021). "In addition, expression of inflammation-related cytokines including IL-17, IL-6, and TNF-α upregulated by application of IMQ was decreased by ANO1 inhibition, showing that psoriasis-like inflammation is alleviated by inhibition of ANO1." (PMID 34281197, 2021). "This study involved an exploration of the effects of FZHFZY on epidermal differentiation and its underlying mechanisms in interleukin (IL)-17A/IL-22/interferon (IFN)-γ/tumour necrosis factor (TNF)-α–stimulated HaCaT cells and in a mouse model of imiquimod (IMQ)-induced psoriasis." (PMID 34456715, 2021). "When psoriasis persists or worsens, IFN-α and VEGF released by activated PDCs and keratinocytes provoke myeloid DCs (MDCs) that express proinflammatory cytokines including TNF-α, IL-1β, IL-6, and IL-23." (PMID 34281197, 2021). "Therefore, we used RT-PCR to assess the mRNA levels of inflammatory cytokines, such as IL-6, TNF-α, IL-17A, and IL-17F, in skin tissues of mice with IMQ-induced psoriasis." (PMID 33995368, 2021). "Patients were included who started TNFα‐i treatment between July 1, 2012 and December 31, 2017, from three Dutch hospitals, and were diagnosed with rheumatic diseases (RD), inflammatory bowel disease (IBD), or psoriasis." (PMID 34302442, 2021). "Furthermore, several pro-inflammatory factors, such as IL-6, IFN-γ, and TNF-α, have been demonstrated to be central to the interaction between keratinocytes and inflammatory cells, and this interaction might be responsible for the initiation, maintenance, and recurrence of psoriasis." (PMID 34667159, 2021). "Considering the repression of MLT on IL-17, NF-κB, and TNF signaling pathways, MLT could be a potential candidate treatment for patients with autoimmune diseases including psoriasis and vitiligo." (PMID 34899707, 2021). "Isoflavone reduced the activity of MAPK, NF-κB, and JAK-STAT by IL-22, IL-17A, and TNF-α in epidermal keratinocytes; TNF-α and NF-κB levels were high in the skin lesions of patients with psoriasis, and isoflavone extracts play a large role in their inflammatory responses." (PMID 34209224, 2021). "Even if it is well known that the TNF-α/IL-23/IL-17 axis is involved in the pathogenesis of psoriasis and PsA, it is not so easy to compare the efficacy of a selected biologic drug for skin and joints." (PMID 34680599, 2021). "TNF alpha concentration in patients with psoriasis decreases after UVB irradiation, independent of polymorphisms in the VDR gene, except for the presence of the TaaI/Cdx-2 AA genotype and TaqI TT genotype." (PMID 34208603, 2021). "Anti-TNF-α and anti-TNF-α receptor drugs are now being used to treat psoriasis." (PMID 34834393, 2021). "Anti-TNF has been successfully used for both psoriasis and IBD management, as TNF has an important role in the pathogenesis of both diseases - infliximab, adalimumab, and certolizumab may all induce remission of both diseases." (PMID 34548985, 2021). "In fact, IL-1 has the ability to stimulate MCs to produce IL-6, TNF, and IL-33 without degranulation, building a powerful proinflammatory network—an effect that increases with stress, which exacerbates psoriasis." (PMID 34360845, 2021). "Here the authors show that phosphorylation of NFκBp65 in cDC2 before therapy is an indication of non-response to the anti-TNF therapy adalimumab in patients with psoriasis." (PMID 34362923, 2021).
psoriasis (continued). "This may be because most of the study subjects were patients with mild psoriasis, so a low PASI score indicates low disease activity with low TNF-a levels, meaning that the degree of correlation could be related to the patient sample selection." (PMID 34372872, 2021). "The impact of anti–TNF-α treatment on the lipid profile of psoriasis patients has not been concluded so far." (PMID 34803716, 2021). "The patients who develop psoriatic lesions can continue anti-TNF treatment, using topical treatment to control secondary psoriasis, unless the latter is not responding or is so severe, extending over 5% of body surface or complicating with pustules." (PMID 33477990, 2021). "In moderate-to-severe psoriasis, increased levels of pro-inflammatory markers and cytokines, such as TNF-α, IL-6, IL-17, IL-23, PCR, and others, have been detected not only in skin plaques, but also in the blood and other biological fluids, such as saliva." (PMID 34829740, 2021). "In addition to TNF-α, IL-1β, and IL-6, pDCs produce a significant amount of interferon (IFN)-α, which is necessary to initiate the inflammatory response in psoriasis." (PMID 34371756, 2021). "In summary, these findings indicate that CD100/PlxnB2, TTP, TNF, miR-155, and SAA might be potential therapeutic targets for psoriasis." (PMID 34707607, 2021). "In patient 1, the normalization of TNF levels was accompanied by increased IFN-α/β secretion and paradoxical psoriasis (a recently described possible consequence of anti-TNF antibodies), which might require appropriate management (jakinhibs, eventually)." (PMID 34066649, 2021). "Th17 cells, as well as Th1 cells and keratinocytes, secrete TNF-α, IFN-γ, IL-1β, IL-6, IL-12, IL-17A, IL-22, IL-23 participating in pathophysiologic processes of psoriasis and current biological therapies as T cell-directed agents have demonstrated excellent efficacy in psoriasis." (PMID 33685393, 2021). "A fifth anti-TNF-α agent, golimumab, is currently approved for the treatment of psoriatic arthritis but not psoriasis." (PMID 34938746, 2021). "Exosomes derived from human epidermal keratinocytes treated with psoriasis-related cytokines, such as IL-17A, IL-22, IFN-γ, and TNF-α, stimulate normal human neutrophils, followed by NF-κB and p38 MAPK signaling activation, leading to the production of TNF-α, IL-6, and IL-8, and NET formation." (PMID 34944704, 2021). "It has been found that the local concentrations of adiponectin and TNF-α in sWAT were not significantly different between the control group and the psoriasis and/or metabolic syndrome group." (PMID 34372872, 2021). "Downregulation of ULK1 with siRNA did not affect the expression of most psoriasis-related cytokines in PHK without stimulation but increased the transcripts of TNF and CXCL8 in the presence of IL-17A." (PMID 34421918, 2021). "Therefore, this study involved the use of IL-17A/IL-22/IFN-γ/TNF-α–induced HaCaT cells and mice with IMQ-induced psoriasis." (PMID 34456715, 2021). "Psoriasis is increasingly regarded as a chronic inflammatory systemic illness mediated by multiple inflammatory cytokines, such as TNF-α, rather than a simple skin condition." (PMID 34834393, 2021). "In addition, TNF is the target of three biologics (ADA, INF, and CTL) indicated for the treatment of moderate-to-severe psoriasis." (PMID 34577605, 2021). "The biologic drugs targeting TNF, IL-12/IL-23, and IL-17 have been approved for the treatment of psoriasis in the last few years, but not all patients respond to treatment with biologics." (PMID 34640327, 2021). "Interestingly, type-I IFN is the main inflammatory pathway involved in acute and unstable psoriasis forms such as guttate, erythrodermic psoriasis, and PPP induced by anti-TNF-α therapies." (PMID 34409425, 2021). "The local policies in one included hospital advised psoriasis patients not to initiate treatment with a TNFα inhibitor but with an interleukin inhibitor." (PMID 34302442, 2021).
psoriasis (continued). "Therefore TNF-α antagonists (adalimumab, infliximab, and etanercept) were approved by the US Federal Drug and Administration (FDA) for the treatment of psoriasis and rheumatic arthritis." (PMID 33450863, 2021). "The levels of IL-6, TNFα and IL-17 were significantly reduced as compared to the vehicle group, suggesting SHR168442 suppressed the production of Th17 pathway related cytokines in IL-23-induced Psoriasis-like skin inflammation mice." (PMID 33911101, 2021). "Moreover, TNF is the target of three biopharmaceuticals (ADA, INF and CTL) indicated in the treatment of moderate-to-severe psoriasis." (PMID 33921427, 2021). "These anti-TNF therapeutics, and biosimilars of infliximab, etanercept and adalimumab that have been approved recently, are successfully used to treat autoimmune diseases, including RA, juvenile RA (JRA), IBD, psoriasis, and ankylosing spondylitis (AS)." (PMID 32528961, 2020). "In psoriasis, TNFα, and inducible nitric oxide synthase (iNOS)-producing DCs (Tip-DCs) and 6-sulfo LacNAc DCs (slanDCs) are reported as iDCs, and they induce T cells to secrete IL17, IL22, TNFα, and IFNɤ." (PMID 33050592, 2020). "In individuals with early type of psoriasis (under 40 years of age) LCs do not show the ability to migrate under the influence of stimuli (chemical allergens, IL-1b and TNF-α)." (PMID 31963581, 2020). "Furthermore, cytokines secreted by T helper 1 (Th1) cells, including interferon-γ (IFN-γ) and tumor necrosis factor-α (TNF-α), are increased in the psoriatic lesions and peripheral blood of psoriasis patients." (PMID 32917058, 2020). "For instance, TTP regulation of TNF in keratinocytes, but not in myeloid or dendritic cells, was shown to protect mice from exacerbation of psoriasis-like pathology, development of spontaneous systemic inflammation, and dactylitis." (PMID 32983182, 2020). "Inflammation biomarkers that have been previously used in psoriasis patients include serum levels of C-reactive protein (CRP), haptoglobin, complement 3 (C3), C4, TNF-α, IL-6, IL-8, IL-12, elafin, neutrophil-lymphocyte ratio (NL), and platelet-lymphocyte ratio (PL)." (PMID 32881431, 2020). "Dysregulated Th17 cells and IL-17 synthesis in the skin, synovial space and endothelium promote synthesis of pro-inflammatory cytokines namely IL-1β, TNF and IL-6 and neutrophil chemoattractants such as IL-8, CCL20 and CCL2 as observed in psoriasis and psoriatic arthritis." (PMID 33737877, 2020). "Moreover, by using different inflammatory stimuli, such as IL-17 and TNFα instead of LPS, the HSOC can be used as a model for specific skin disorders, such as psoriasis." (PMID 32218380, 2020). "Chronic immune responses are absent in paradoxical psoriasis induced by TNF‐α blockers, with innate inflammatory processes predominant and not followed by expansion of autoreactive T cells." (PMID 31577850, 2020). "In this study, we investigated the immunological and genetic profiles of three HS patients without psoriasis who developed paradoxical psoriasiform reactions following anti‐TNF‐α therapy with adalimumab." (PMID 31577850, 2020). "Smits and colleagues established psoriasis and atopic dermatitis models using N/TERT epidermal skin by adding Th1/Th17 (TNF-α, IL-6, IL-1α, IL-17, and IL-22) cytokines and Th2 (IL-4 and IL-13) cytokines, respectively, during the final stage of the skin maturation." (PMID 32509598, 2020). "The levels of cytokines IL-17A, IL-23, and TNF-α were significantly higher in the IMQ groups, which could reflect the pro-inflammatory status in the psoriasis mouse model." (PMID 31956331, 2020). "Thus, this “cytokine converter” exerts its function only when both TNF and IL22 coexist (AND-gate logic), which is a characteristic of psoriasis." (PMID 32185403, 2020). "Therefore, the regulatory mechanism of IL-22 on anti-apoptosis of keratinocytes occurs in the presence of TNF-α and IFN-γ in psoriasis." (PMID 32632545, 2020).